ATR (ATR checkpoint kinase)
Diseases named in the same sentence as ATR in open-access papers (continued):
Sharing a sentence is not in itself a finding about the gene and the disease.
cancer (continued). "ATRi elicit anti‐tumour effects in both pre‐clinical cancer model systems and in early phase clinical trials, without eliciting severe, non‐tumour toxicity; this is presumably because ATR inhibition exacerbates pre‐existing tumour cell‐specific RS to the point where tumour cells are not viable." (PMID 35567571, 2022). "Due to its extensive role in DDR, ATR inhibition has great potential in cancer treatment." (PMID 36082941, 2022). "Given that ATM/Chk2 activation profiles are the same in topotecan-sensitive and -resistant cells, ATR/Chk1 activation may dictate and distinguish DNA damage responses in cancer cells with TOP1 inhibition." (PMID 35844787, 2022). "Dysregulation of ATR has been found across different cancer types." (PMID 35458687, 2022). "ATR limits origin firing across active replicons in unperturbed human cancer cells and fibroblasts." (PMID 36130512, 2022). "Nevertheless, we rationally hypothesized that this ATR mutation, found in MSI + cancers, could be critical during drug response, especially for molecules known to be ATR-CHK1 inducers such as SN-3837." (PMID 35361811, 2022). "Although it was known that inhibition of ATR, CHK1, and WEE1 reduces dNTP concentrations in cancer cells, our findings that ATR kinase activity is essential to limit dU contamination and that dT partially rescues ATRi-induced CD8+ T cell and cancer death are, in our view, unanticipated." (PMID 36130512, 2022). "For example, inhibiting the activation of pathways between ATM and ATR could enhance the sensitivity of cancer cells to chemotherapeutics." (PMID 35303867, 2022). "Thus, inhibition of DNA damage repair pathways is an effective therapy for ALT cancer, for example an ATR targeting inhibitor has been shown to block ALT cell proliferation." (PMID 36399511, 2022). "Targeting of the ATR is a promising strategy for the treatment of cancer." (PMID 36539893, 2022). "In addition, ATR inhibitor AZD6738 (ATRi) combines with radiation to generate CD8+ T cell-dependent responses in immunoproficient mouse models of cancer." (PMID 36130512, 2022). "As MTHFD2 inhibitors do not introduce RS in nontumorigenic cells, we propose that their combination with ATR or Chk1 inhibitors may improve the cancer selectivity and therapeutic index of these compounds." (PMID 35228749, 2022). "Ataxia telangiectasia and Rad-3 related kinase (ATR) signals DNA lesions and replication stress (RS) to the S and G2/M checkpoints and DNA repair pathways making it a promising target to exploit the dysregulated DNA damage response in cancer." (PMID 35954206, 2022). "In addition to PARP, oncogene-induced replication stress activates the ATR-CHK1 checkpoint pathway, raising the possibility to exploit the use of CHK1 or ATR inhibition in cancers harboring activated oncogenes." (PMID 36186482, 2022). "In this regard, the exposure to these new cancer vulnerabilities might aid in the development of new cancer therapies, as exemplified by using ATR inhibitors to treat MDS." (PMID 35879727, 2022). "Thus, inhibition of ATR will abrogate the G2/M cell cycle checkpoint and will increase the sensitivity of cancer cells to IR." (PMID 36249060, 2022). "However, as MTHFD2 inhibitors cause cancer-specific replication stress, triggering the ATR-Chk1 signaling cascade, we observed a strong synergy between MTHFD2 inhibitors and ATR and Chk1 inhibitors." (PMID 35228749, 2022). "However, when cancer cells escape this protective pathway and switch to becoming addicted to ATR/CHK1 activity, to allow them to cope with high levels of DNA replication stress, T505 phosphorylated RelA will contribute towards tumour survival." (PMID 36240065, 2022).
cancer (continued). "VX-970, a small-molecule ATR inhibitor, is currently being tested with promising results in many clinical trials in combination with chemotherapeutic drugs against resistant and aggressive cancers." (PMID 36499000, 2022). "The extent to which high replication stress characterizes human PTCL is unknown, though our preliminary analysis of ALCL cell lines (a form of PTCL) suggests a degree of sensitivity of these cancers to ATR/CHK1/Wee1 inhibitors." (PMID 35510955, 2022). "Because SLFN11-deficient cancer cells rely on the ATR pathway to modulate their DNA replication and damage repair processes in response to replication stress, the combination of ATR inhibitors with DDAs is selectively active in SLFN11-negative cancer cells." (PMID 35768579, 2022). "Inhibition of ATR or CHK1 increases the sensitivity of cancer cells to TOP1 inhibitors." (PMID 36015333, 2022). "Among those, the main function of AKT, ERK1/2, and NF-κB signalings is to block apoptosis induction in the irradiated cancer cells, while the primary functions of the ATM, ATR, and DNA-PK signalings are to promote the cell cycle checkpoint activation and DNA repair in cancer cells." (PMID 35328212, 2022). "Thus, the ATR-Chk1 signaling axis is important to prevent DNA damage-induced A3A expression in cancer cells." (PMID 34389714, 2021). "Based on promising early clinical trial results in other cancer types, more extensive testing using inhibitors of ATR (AZD6738) and WEE1 (AZD1775) was performed on 15 PDCLs defined as high and low replication stress based on the replication stress signature score." (PMID 33039466, 2021). "If the levels of TopBP1 are higher than the optimal level for ATR activation, these cancer cells may, to some extent, become defective in checkpoint response to replicative stress." (PMID 33556369, 2021). "Therefore, cancers with loss‐of function mutations in HR pathway components such as BRCA1, ATM, ATR, RAD51, and FANC genes are susceptible to treatment with PARP inhibitors." (PMID 33660437, 2021). "Earlier in the review, we discussed the concept of targeting ATR in ATM mutant cancers." (PMID 34572943, 2021). "Due to their proliferative nature and being subject to oncogenic forces that either lead to heightened levels of reactive oxygen species or deregulated S-phase entry and/or progression, cancer cells are particularly vulnerable to ATR inhibition, experiencing extensive DNA and chromosomal damage." (PMID 33888558, 2021). "ATR inhibitors are in clinical trials for the treatment of cancers, with patient selection hypotheses including ATM deficiency and high replication stress." (PMID 34329458, 2021). "We infer that majority of the conserved ATM/ATR residues mutated in cancer are buried within the respective enzyme complexes, irrespective of the cancer type." (PMID 33742106, 2021). "It is interesting to test whether targeting APE2 via small molecule inhibitor such as Celastrol can sensitize cancer cells to ATR inhibitors." (PMID 34796173, 2021). "Several studies have shown that ATR inhibition could increase the radiosensitization of cancer cells." (PMID 33546122, 2021). "Consequently, the ATR/CHK1 pathway represents a vulnerability for tumors in which latent RS can be awakened and, consistently, MYC-driven cancers are highly sensitive to ATR and CHK1 inhibitors as single agents." (PMID 34201047, 2021).
cancer (continued). "The justification for targeting ATR in cancer cells centers around ATR's functions in protecting stalled DNA replication forks, regulating replication origin firing, and controlling the transition of cells from G2 phase into mitosis by enforcing the G2/M cell cycle checkpoint." (PMID 33888558, 2021). "In breast-cancer susceptibility gene 2 (BRCA2)-deficient cancer cells, the inactivation of replicative stress response factors (e.g. poly (ADP-ribose) polymerase [PARP1] or ATM and Rad3-related [ATR] inhibition) triggers cyclic GMP-AMP synthase (cGAS)-STING-mediated innate immune responses." (PMID 34970273, 2021). "We suggest that the ROS-based activation of ATR/Chk1 activation evidenced here may also contribute toward the observed chemo-/radioresistance of cancer cells." (PMID 34622778, 2021). "We explored the role of ATR in mediating TMZ resistance and whether ATR inhibitors (ATRi) could reverse this resistance in multiple cancer lines." (PMID 34676045, 2021). "Moreover, cancer cells with high levels of oncogene-driven replication stress rely on ATR activity for survival." (PMID 34819497, 2021). "The cancer-associated residues are next to the kinase domain residues ATR G2375 and ATM G2925, respectively, providing further support for the functional relevance of the FAT kinase domain interface int the ATM, ATR, and Mec1 enzyme complexes." (PMID 33742106, 2021). "Several studies using different cancer models suggest that PARPi-resistant tumors are strongly dependent on the ATR/CHK1/WEE1 pathway, and that inhibition of these kinases may restore PARPi sensitivity." (PMID 34439286, 2021). "Additionally, the nuclear ATM/ATR/CHK1 kinase signaling pathway can modulate PD-L1 expression following DNA damage by phosphorylating STAT1/3 (in the cytoplasm) in cancer cells." (PMID 34930377, 2021). "We hypothesised that ALK-driven NB, which often involves MYCN amplification, may also represent a situation where cancer cells are more dependent on the integrity of ATR-regulated checkpoint responses and therefore sensitive to ATR inhibitors." (PMID 34819497, 2021). "Moreover, combination with poly(ADP-ribose)polymerase (PARP) or ATR inhibitors is a basis synthetic lethality in some cancers." (PMID 33513745, 2021). "Recent studies have shown that activation of ATM/ATR, besides regulating the cell cycle, could induce autophagy and help cancer cells survive; this makes them important targets for future anti-cancer therapies." (PMID 34575923, 2021). "These include connecting cancers with HRD or STAG2 deficiency with PARP inhibitors, epigenetic dysregulation with histone deacetylase or EZH2 inhibitors, and DNA checkpoint abnormalities with ATM or ATR inhibitors, to name a few." (PMID 34101093, 2021). "Alternatively, the protection of cancer cells from DNA damaging conditions by APE2 may be mediated from its critical function in the ATR-Chk1 DDR pathway indirectly due to the role of ATR in genome integrity." (PMID 34796173, 2021). "Furthermore, it has been found that ATR inhibitors are selectively toxic to cancer cells harboring mutations in the ATM tumor suppressor, in part because ATM and ATR share some overlapping targets." (PMID 33888558, 2021). "Inhibition of ATR shows promising results in cancer therapy." (PMID 34072430, 2021). "The second and third most frequent mutations found in different cancer cell lines are ATM and ATR." (PMID 34887439, 2021). "Furthermore, the addition of the ATM kinase-specific inhibitor KU55933 or another ATM/ATR dual inhibitor CGK733, caused the increase of apoptosis in these cancer cells." (PMID 33912571, 2021). "Cancer cells may compensate the loss of ATM by upregulating ATR, indicating that ATR inhibitors may display efficacy in ATM-deficient tumors, including PCa." (PMID 33672917, 2021). "Therefore, ATR is an attractive therapeutic target for cancer treatment, especially in combination with DNA-damaging agents." (PMID 34026622, 2021).
cancer (continued). "Increased replication stress in cancers makes them sensitive to ATR inhibitors." (PMID 34027408, 2021). "Since ATR inhibition lowers cellular H2S concentrations, this may be an unexamined aspect of ATR inhibition in cancer therapeutics." (PMID 34829691, 2021). "In addition, these findings establish a key pro-resection function for ATR, especially in cancer cells undergoing intrinsically high levels of ATR–CHK1 signaling due to elevated oncogene-induced replication stress." (PMID 32743550, 2020). "Emerging data suggest that olaparib-resistant cancer models can be re-sensitized to olaparib when combined with AZD1775 or AZD6738, leading to early phase clinical trials combining ATR inhibitors and PARPis in different cancers (NCT02723864, NCT03462342, NCT03682289, NCT02576444)." (PMID 32605126, 2020). "In addition, since ATR inhibition enhances replication stress, as anticipated in pre-clinical trials, several studies analyze cancer cell sensitization by these drugs to DNA damaging agents such as cisplatin, gemcitabine, and radiation." (PMID 32932697, 2020). "Our study reveals a potential pharmacological target in the regulation of mitochondria-associated ATR by phosphatase PP2A that may imply new therapeutic strategies against diseases involving apoptotic cell death and cancer." (PMID 32984322, 2020). "Hence, inhibition of ATR has been recognized as an attractive pharmacological strategy for amplification of RS in cancer cells." (PMID 32628111, 2020). "We then examined the contribution of ATR in the migration of cancer cells." (PMID 32973141, 2020). "Interestingly, while moderate and high ATR levels in cancer cells were similarly correlated with better outcome, moderate ATR levels in stromal fibroblasts were correlated with better patient outcome than those who expressed high ATR levels." (PMID 32414408, 2020). "Therefore, the synthetic lethal interaction can be exploited as the result of increased dependency on the S and G2/M checkpoints mediated by ATR due to the heightened replication stress as the cancer cells enter S phase." (PMID 32883316, 2020). "Finally, we show that ATR is essential for neurogenesis and cancer cell migration, two processes in which cells and their nuclei must squeeze through tight spaces." (PMID 32973141, 2020). "This indicates that the ATR expression level in both cancer as well as stromal fibroblasts could be of great prognostic value for patients with LABC treated with neoadjuvant therapy." (PMID 32414408, 2020). "ATR is an essential DDR kinase activated in cancer cells with high level of replication stress." (PMID 32366852, 2020). "Thus, ATR inhibition is an emerging target in cancer therapy, with multiple ATR inhibitors currently undergoing clinical trials." (PMID 33137164, 2020). "Since long-term ATR inhibition affects the abundance of E2F targets, many of which are components of the HR machinery, the ability of cancer cells to upregulate E2F transcription could, in principle, bypass the effects of long-term ATR inhibition." (PMID 32743550, 2020). "Our recent studies have revealed that in ATM-deficient cancer cell lines, olaparib is cytostatic not cytotoxic and that combination of olaparib with an ATR inhibitor is needed to induce cell death." (PMID 32183301, 2020). "Cis-ATR is not directly mutagenic, but it allows cancer cells to evade apoptosis, a very important hallmark of carcinogenesis." (PMID 32426354, 2020). "Furthermore, the NBN 343 serine residue, a known substrate of ATR 36, was also highly phosphorylated in cancer specimens, indicating that the signaling cascade via ATR was activated." (PMID 32089736, 2020). "Altogether, these observations suggest ATR inhibition might be synergistically lethal to cancer cells with various replication vulnerabilities." (PMID 32015826, 2020).
cancer (continued). "Therefore, targeting cis-ATR as an adjuvant in treating cancers by irradiation or chemotherapy should preferentially kill cis-ATR-addicted cancer cells, with minimal effects on the normal functions of nuclear trans-ATR in cells." (PMID 32426354, 2020). "To assess whether Cyclin E1 overexpression affects the sensitivity of cancer cells to inhibitors of cell cycle checkpoint kinases, we induced Cyclin E1 overexpression and inhibited ATR and WEE1 kinases using VE-822 and MK-1775 respectively." (PMID 32964114, 2020). "Given the critical role of Pin1 in maintaining the balance between cis- and trans-ATR in the cytoplasm, manipulation of Pin1 subcellular level or activity could be another means to control cis-ATR formation for cancer therapeutics." (PMID 32426354, 2020). "Cancers that harbor DDR mutations might also benefit from targeting multiple DDR components: for example, inhibition of ATR after PARP inhibitor therapy can overcome PARP inhibitor resistance in tumors with a BRCA-mutant genetic background." (PMID 32731592, 2020). "Our findings could provide biomarkers to ultimately help create effective treatment plans for cancer therapy with ATR inhibitors." (PMID 33137164, 2020). "In addition, the ATM/ATR/CHK1 pathway has been shown to be essential for upregulation of PD-L1 on cancer cells after treatment with DNA-damaging agents." (PMID 33224881, 2020). "Cis-ATR (ATR-H), potentially, can be such a target protein that is novel and could be effective in cancer treatment." (PMID 32426354, 2020). "In addition, increased E2F transcription is a common feature of cancers undergoing increased levels of intrinsic replication stress and ATR signaling." (PMID 32743550, 2020). "Our work lays the foundation for personalized deployment of ATR inhibitors in cancer therapy." (PMID 33137164, 2020). "However, activation of CHK1 was shown to circumvent replication catastrophe associated with ATR inhibition and co-inhibition of CHK1 produced synthetic lethality in cancer cells through CDK-dependent origin firing." (PMID 32628111, 2020). "Our observations suggest that ATR activity might be therefore beneficial for cancer cell migration, thus implying that ATR might play opposite roles in cancer progression, by preventing genome instability and by promoting metastasis." (PMID 32973141, 2020). "ATR inhibitors (ATRi) could be an option for killing cancer cells with an inherently large amount of DNA damage, due to the pivotal role of ATR in the DNA damage response." (PMID 33137164, 2020). "Moreover, multivariate Cox regression analysis showed that the ATR expression level in stromal fibroblasts is a significant independent predictor of OS and DFS, while ATR level in cancer cells was an independent prognostic factor only for OS, but not for DFS." (PMID 32414408, 2020).